SNORA70F (small nucleolar RNA, H/ACA box 70F)
Synonyms: U70F
Gene: Small nucleolar RNA gene on chromosome 2 (164,687,643 to 164,687,777, reverse strand). Ensembl gene ENSG00000206869.
Gene Ontology:
Biological process: RNA processing
Cellular component: nucleolus
Homologues: Orthologues: chimpanzee SNORA70 (99% identical), macaque SNORA70 (90% identical). Paralogues in human: SNORA70B (88% identical), SNORA70H (87% identical), SNORA70C (87% identical), SNORA70G (87% identical), SNORA70J (87% identical), SNORA70I (86% identical), SNORA70 (85% identical), SNORA70 (84% identical), SNORA70 (83% identical), SNORA70D (83% identical), SNORA70E (82% identical), SNORA70 (81% identical), and 14 more.